PTPN13 (protein tyrosine phosphatase non-receptor type 13)
Diseases named in the same sentence as PTPN13 in open-access papers (continued):
Sharing a sentence is not in itself a finding about the gene and the disease.
cancer (continued). "Western blot study found that the expression level of PTPN13 decreased significanly in all cancer tissues compared with the paired adjacent normal tissues, suggesting that miR-26a may negatively regulate PTPN13 expression." (PMID 27285768, 2016). "Thus, HPV positive cells served as an additional test of the function of PTPN13 in cellular signaling in the context of virally-mediated cancer." (PMID 22279592, 2012). "Finally, although PTPN13 is primarily studied in cancer, its roles in multiple signaling pathways suggest its implication also in other pathologies, for instance, neurodegenerative diseases where recent studies pointed to a potential role in tau phosphorylation." (PMID 33322542, 2020). "We carried out a preliminary analysis (PTPN13 expression, growth rate, and migratory capacity) in four representative HGSOC cell lines available at the “SIRIC-Montpellier cancer” cell bank: COV-318, KURAMOCHI, OVCAR-3, and OVCAR-8 cells." (PMID 37895093, 2023). "Here, we used the OVCAR-8 (low PTPN13 expression) and KURAMOCHI (high PTPN13 expression) HGSOC cell lines to investigate PTPN13’s role in ovarian carcinogenesis, particularly in cancer cell mobility, invasiveness, and platinum sensitivity." (PMID 37895093, 2023). "A recent study demonstrated PTPN13 involvement in cisplatin sensitivity of HNSCC cell lines (WSU-HN6 and CAL-27) where cancer-derived IgG inhibition upregulates PTPN13, resulting in the inhibition of the SRC/PKD1/AKT pathway." (PMID 33322542, 2020). "The protein-tyrosine phosphatase FAP-1/PTP-Bas/PTPN13 interacts with human Fas protein (CD95) and prevents its export from the cytoplasm to the cell surface in cancer cells." (PMID 26716643, 2016). "Thus, HPV infection or functional mutations of PTPN13 in non-viral cancers may predict taxane sensitivity." (PMID 25436983, 2015). "The CNV percentage in pan-cancer indicated that heterozygous amplification in cancers were widely found in genes PTPN1, PTPN7, PTPN12 and PTPN14 in most cancers, while heterozygous deletions were widely found in genes PTPN13, PTPN20, PTPN22 and PTPN23." (PMID 37884566, 2023). "Moreover, PTPNs expressions except for PTPN5, PTPN13, and PTPN21 were significantly upregulated in the tumorous compared with those in normal tissues in 20 cancers in the TCGA pan-cancer." (PMID 37884566, 2023). "Interestingly, positively correlated loci represented cancer driver genes (MYC, PRKCD, RB1, CDK6), molecules involved in immune response (MALT1, PIK3CG), as well as cellular and hormonal signaling (HGF, PTPN13, IGF1, SMAD1, ESR1, CTGF)." (PMID 34368147, 2021). "In this review, we focus on protein tyrosine phosphatase non-receptor 13 (PTPN13) because many studies have highlighted its possible dual role in cancer." (PMID 33322542, 2020). "Among Cancer Gene Census genes, 1346 events were detected in 947 different loci, with the most recurrent ones being those in CLTCL1 (24 cases), CSMD3 (21 cases), MYH9 (20 cases), ANK1 (19 cases), TPR (19 cases), MYH11 (18 cases), PTPN13 (18 cases), and POLQ (17 cases)." (PMID 33809641, 2021). "Besides, it would be interesting to further investigate whether or not Stat3 could regulate PTPN13 in other cancer cells." (PMID 24191246, 2013).
infection (8 papers, 2017 to 2025). The state of being infected such as from the introduction of a foreign agent such as serum, vaccine, antigenic substance or organism. "In this study, we found that CASP2 and PTPN13 were the targets of lncRNAs and down-regulated during infection." (PMID 34130627, 2021).
neurological disorders (1 paper, 2022). "Given that tau hyperphosphorylation is a hallmark of several neurological disorders, including Alzheimer’s disease (AD) and traumatic brain injury (TBI), the authors tested whether they could link TBI-induced calpain-2 activation, via PTPN13 cleavage, to tau hyperphosphorylation." (PMID 36755664, 2022).
PTPN13 also shares sentences with these, for which no sentence is quoted: pancreatic cancer (5 papers); adenocarcinoma (4); cyst (3); bacterial infection (2); chronic myeloid leukemia (2); fibrosis (2); Hodgkins lymphoma (2); non-Hodgkin lymphoma (2); Burkitt lymphoma (1); Co-infection (1); colorectal polyps (1); colorectal tumors (1); desmoid tumor (1); endocarditis (1); Familial adenomatous polyposis (1); follicular lymphoma (1); hematopoietic cancers (1); Hepatic (1); hepatoblastoma (1); idiopathic pulmonary fibrosis (1); invasive breast carcinoma (1); Kaposi's sarcoma (1); liver disease (1); lymph node metastases (1); mantle cell lymphoma (1); metastatic tumors (1); microsporidia infections (1); neurodegenerative disease (1); osteoma (1); osteosarcoma (1).
A further 12 diseases each share a sentence with PTPN13 in 1 paper.